S100B (S100 calcium binding protein B)
Diseases named in the same sentence as S100B in open-access papers (continued):
Sharing a sentence is not in itself a finding about the gene and the disease.
tumor (continued). "The higher level of S100B tumor marker was also not predictive for DFI or OS in plasma samples obtained during the second (p = 0.706 and p = 0.584, resp)." (PMID 39387479, 2024). "In total, five populations were designated tumour clusters, which had various features: (TumourC0) CD74 and APOD; (TumourC1) IF16, JUN and HSPA1A; (TumourC2) S100B and SCRG1; (TumourC3) NEAT1 and MALAT1; and (TumourC4) WFDC2 and RNASE1 (HLA‐DRA, CD68, CD3D, CD3E)." (PMID 37784253, 2023). "Following radiation therapy, the release of S100B and HMGB1 from injured brain parenchyma or tumor cells may activate downstream RAGE-mediated inflammatory pathways as occurs in stroke and trauma." (PMID 36652782, 2023). "Quantification of S100B + cells on scanned whole-sections confirmed that S100B + cells could be detected in normal APG, as well as in gonadotroph, corticotroph, and Pit1 tumours." (PMID 35139928, 2022). "While we identified a first group of gonadotroph tumours with almost no S100B + cells, we found a second group that presented a wide distribution of S100B + cells ranging from 0.005 to 18.85% within different areas analysed." (PMID 35139928, 2022). "Analysis of the 26 gonadotroph tumours confirmed interpatient heterogeneity, with a subset of tumours displaying almost no S100B expression within the areas quantified and a group of lesions presenting areas with variable percentages of S100B + cells." (PMID 35139928, 2022). "In contrast to the salient OPC features in glioma, the tumor cells in our disease model do not abundantly express differentiated cell markers such as Olig2, S100β, and CC1." (PMID 33863883, 2021). "Immunofluorescence stainings for CD3 and S100B verified the presence of CD3+ T-cells within the S100B+ SC stroma in GNs, while CD3+ T-cells were only sparsely detected in the tumor cell portion of NBs." (PMID 33712610, 2021). "Interestingly, these immunosuppressive protein markers were also significantly (* p < 0.05) correlated with an increased expression of certain tumor markers, such as CD44, B2M, HER2/ErbB2, S6, B7-H3, ER alpha and S100B." (PMID 34944780, 2021). "Tumors from both models were indistinguishable, both containing high numbers of Tomato+ tumor cells expressing both S100b and Sox10, which was expected as Tyr and c-Kit promoters targets the same population of McSCs in the hair follicle." (PMID 31685822, 2019). "VDAC1-based peptide tumor treatment eliminated GSCs, as reflected in the marked decrease in the expression levels of all tested stem cell markers, namely Sox2, Nestin, CD133, Klf4, S100B and NGFR." (PMID 28412744, 2017). "A considerable amount of S100B positive cells were seen within the tumor, however none of the cells co-localized with GFP." (PMID 25875288, 2015). "A possible difference in tumour burden between the two groups was checked by real-time PCR of S100B and the analysis did not reveal significant difference (P=0.91; Mann–Whitney)." (PMID 22045183, 2011). "Preoperative S100β levels did not correlate with tumour volume (p = 0.32), edema volume (p = 0.72), or tumour and edema volume together (p = 0.81) as measured by MRI." (PMID 17020600, 2006). "S100β levels were affected by the quality of surgical plane but not by the need to resect at a less-accessible tumour location (convexity located versus deep-seated)." (PMID 17020600, 2006). "Preoperative S100β levels did not correlate with the tumour characteristics demonstrated by preoperative MRI (for example, tumour volume, edema volume, ventricular asymmetry, and/or midline shift)." (PMID 17020600, 2006). "Moreover, these three MPNSTs presented few somatic SNVs, similar to other groups described in this tumor type (median of 40–60 variants) and presented negative SOX10 and S100B staining, as expected." (PMID 37798904, 2024). "Additionally, the downregulation of S100B, IL31RA, and CREB5 found here may also promote anti-tumor responses and reduce tumor progression." (PMID 37762335, 2023).
tumor (continued). "Another benefit to tumor cells from S100B-dependent inhibition of IL6 secretion could be to prevent IL6 activation of B cells, T lymphocytes, and dendritic cells as a means to avoid an anti-tumor immune response at an early stage or in regions with little or no signs of a stress-response." (PMID 34411141, 2021). "Interestingly, tumours developed in Ager−/− mice released smaller amounts of S100B, but not HMGB1, at 25 dpi compared with those derived from WT mice, suggesting that the presence of RAGE influences the secretion of S100B from tumour masses." (PMID 32159297, 2020). "As such, it was not possible to study the values of serum S100B after tumor progression." (PMID 27401156, 2016). "This fact could indicate the presence of multipotent stem cells that have suffered a second-hit mutation, although a dedifferentiation from S100β+/NF1− Schwann cells, also present in the tumor, can not be excluded." (PMID 22550514, 2012). "Preoperative S100β levels did not correlate with either tumour and/or edema volume." (PMID 17020600, 2006). "Identification of an enrichment in S100B + folliculostellate cells in areas also enriched in ERα-expressing and FSH-expressing cells may suggest a role for these cells in maintaining a more differentiated, functioning or closer to the normal phenotype state of gonadotroph tumour cells." (PMID 35139928, 2022). "Only tumor SP‐01 presented strong dual staining for S100B and SOX10, contrary to classic MPNSTs that present negative or focal expression, like S100B expression in the SP‐04 tumor." (PMID 37798904, 2024). "The population of tumor-derived astrocytes was identified by the upregulation of canonical astrocytic markers, including GFAP, AQP4, GJA1, and S100B." (PMID 35803925, 2022). "PDGFRα was also highly coexpressed by the ASCL1+ and OLIG2+ (not shown) tumor cells, whereas GFAP and to a lesser extent S100β and NEUN, although found in some parts of the tumor, did not overlap significantly with SOX2 or ASCL1." (PMID 32573857, 2020).
cancer (83 papers, 2010 to 2026). A tumor composed of atypical neoplastic, often pleomorphic cells that invade other tissues. "S100b is associated with cancers, as well as inflammatory and immune diseases; its levels fluctuate following brain injury or disruption of the blood–brain barrier." (PMID 40503232, 2025). "While S100B was frequently evaluated, its diagnostic performance was inconsistent due to study populations, cancer origins, and methodological thresholds." (PMID 40814421, 2025). "In particular, S100B was found to be linked to better survival in 13 cancers, while S100A10 was associated with worse survival in 19 cancers." (PMID 38684596, 2024). "On other hand, high expression of S100B reveals ovarian malignancy-associated utilizing primary cancers." (PMID 36613714, 2022). "Overexpression of S100B(ββ) protein is associated with several human diseases, such as cancer, inflammatory disorders and neurodegenerative conditions." (PMID 33573254, 2021). "Most studies implicated S100B in inflammation and cancer progression." (PMID 39335163, 2024). "Notably, S100B is one of the S100 proteins that has been implicated in cancer and in neurodegenerative diseases, and therefore there is ample interest in the pharmacological modulation of its activity." (PMID 33467751, 2021). "S100B is used as a diagnostic marker for inflammatory malignant tumors." (PMID 34035661, 2021). "Consequently, aberrant expression levels of S100B have been implicated in avariety of neurological diseases, cancer, and inflammatory disorders." (PMID 30854023, 2018). "In two patients the peak of S100B occurred 14 days after the observed peak of IL-6 which might suggest that IL-6 reflects immune activation but may not be implicated in the local anticancer immune reaction within the cancer tissue." (PMID 32188047, 2020). "Immunohistochemical diagnosis of MM is mostly based on melanocyte-specific markers such as PMEL, MLANA, or TYR, along with relatively unspecific and pleiotropic cancer biomarkers like S100B, and proliferation-related markers like MKI67." (PMID 40004203, 2025). "In the present study, our research has uncovered that GDFT can mitigate postoperative levels of IL-6 and S100B in elderly cancer surgical patients." (PMID 38584828, 2024). "Recently, some studies have also identified the high expression levels of S100-β with malignant tumors." (PMID 35778531, 2022). "S100B is a 10.7 kDa protein, and its expression has been reported in many disorders, including neurological diseases and cancer." (PMID 36613714, 2022). "It has been reported that an S100B-effector protein interaction inhibitor, by interfering with the interactions with S100B and its effector protein, is a potential strategy to treat malignant tumors." (PMID 35368338, 2022). "Considering their biological role, 3 LNM-upregulated genes (ATG10, GATA3 and S100B) are potential markers of aggressive phenotype and increased metastatic potential of cancer cells." (PMID 33658651, 2021). "S100B is one of the members of the S100 protein family and is involved in the progression of a variety of cancers." (PMID 34837947, 2021). "Improving upon the existing compounds will facilitate better design of drugs to target S100B in cancer." (PMID 33450915, 2021). "Interaction of RAGE with its various ligands (including AGE, HMGB1, and S100B) promotes cancer cell growth, invasion, and angiogenesis." (PMID 34035661, 2021). "The study reported here supports a role for elevated S100B levels in suppressing IL6/STAT3 signaling providing additional evidence of S100B in supporting cancer." (PMID 34411141, 2021).
cancer (continued). "Clinical implications of S100 proteins in human cancers were found for the following members: S100A proteins, S100B, S100P, S100G." (PMID 34209679, 2021). "In vitro results showed that Apt-RAGE effectively inhibited S100B-dependent and S100B-independent RAGE/NFκB activation in colorectal HCT116 cancer cells, thus decreasing proliferation and migration of cells." (PMID 34035661, 2021). "The therapeutic targeting of S100B(ββ) with small-molecule inhibitors is being pursued for the treatment of cancers, particularly MM." (PMID 33573254, 2021). "Increase in S100B expression level leads to S100B nuclear accumulation as observed in fully differentiated cells and in cancer cells." (PMID 32486507, 2020). "While HMGB1 induced degradation of muscle proteins in cancer conditions by the activation of the autophagy system, the role of S100B in muscle wasting remained uninvestigated." (PMID 32159297, 2020). "In murine cancer models, HMGB1 and S100B induce muscle wasting and this is associated with elaboration of IL-1β and IL-6." (PMID 33291708, 2020). "For example, S100A4, S100A6, S100A7 and S100B play oncogenic roles in cancer development, whereasS100B, S100A2, and S100A11 are believed as TSGs." (PMID 23894350, 2013). "MKI67 and S100B are low-specificity biomarkers used in several cancer types." (PMID 40004203, 2025). "Therefore, we first analyzed the expression patterns of these proteins in the TCGA‐BLCA and Xiangya BLCA cohorts and found that S100A5, S100A7, S100A11, S100A14‐16, and S100B were significantly higher in carcinoma tissues than normal tissues in both cohorts." (PMID 37414584, 2023). "S100B is a versatile signaling molecule that impacts multiple physiological processes ranging from cardiomyocyte remodeling to neuronal regulation, from immune responses to cancer." (PMID 33466232, 2021). "Cancer-related elevations in S100B and HMGB1 levels have also been reported." (PMID 33291708, 2020). "S100B alone can significantly increase proliferation and angiogenesis in intestinal colon cancer Caco-2 cells, which is considered to be an “ideal bridge” linking colonic inflammation and cancer." (PMID 33294444, 2020). "Finally, we can control some of STAT3 cancer progression through inhibition of the S100B-RAGE pathway." (PMID 32443845, 2020). "The S100B protein is an intra- and extracellular signaling protein thatplays a role in a multitude of cellular processes and abnormal S100B isassociated with various neurological diseases and cancers." (PMID 30854023, 2018). "Further studies are required to design S100B analogs that could potentially act as efficient blockers that disrupt the S100A1-RAGE V domain pathway for the treatment of various human cancers or inflammation diseases." (PMID 29444082, 2018). "S100B has intracellular and extracellular functions, and regulates a variety of processes, including cell proliferation, activation of astrocytes during brain damage and disease, as well as promoting cancer." (PMID 27507242, 2016). "However immunohistochemistry revealed that depletion of PMN-MDSC results in a reduced frequency of proliferating cancer cells, identified by double labeling with S100B- and Ki67-specific antibodies." (PMID 21980263, 2011). "However, the mechanism of action of S100B in cancer is still poorly understood." (PMID 34411141, 2021).
cancer (continued). "Furthermore, S100B expression levels can indicate the malignant grade of malignant tumors." (PMID 25536222, 2014). "In complete responders, skin lesion RNA sequencing after treatment, compared with baseline, identified increased inflammation (CXCL5, CXCL8, IL1A, COL1A1) and downregulated cancer markers (PRAME, S100B, MLANA, STK32A)." (PMID 42316430, 2026). "The cancer cell modules (I) of the two samples are characterized by distinct marker genes, i.e., PMEL, ATP1A1, and SPP1 in sample 1 whereas S100B and PSAP in sample 2, in line with previous studies." (PMID 40033360, 2025). "We observed that a 7-day treatment with BZDRs downregulated anti-tumorigenic ECMs, S100B, COL6A6 and VIT, in both non-carcinoma (MCF10A) and carcinoma cells (MCF7 and MDA-MB231) (blue boxes, * p < 0.05; ** p < 0.01; *** p < 0.005)." (PMID 40583063, 2025). "Studies have indicated that silencing S100B and HMGB1 delays diabetic complications and cancer progression." (PMID 39335163, 2024). "We evaluated S100B expression (RNA-seq V2, RSEM, log2) in 10,071 patient-derived samples of 28 different cancers from the TCGA repository." (PMID 36899866, 2023). "Chromogranin A, synaptophysin, S-100B protein and GFAP are well known neuroendocrine markers involved in cancer and in neurological diseases." (PMID 31263455, 2019). "Indeed, S100B is the ligand of RAGE, the receptor for advanced glycation end-products; at high levels, S100B induces muscle atrophy and other hallmarks of cancer cachexia." (PMID 35923848, 2022). "Furthermore, S100B plays an essential role in colon carcinogenesis by promoting NFκB-mediated transcription through the RAGE signaling, affecting various phenotypes of cancer such as proliferation, metastasis, and angiogenesis." (PMID 34035661, 2021). "We found that S-100B protein and NSE serum concentrations were elevated in PNS patients without diagnosed malignancy, and S-100B additionally in patients with peripheral nervous system manifestation of PNS." (PMID 30374596, 2019). "However, high-throughput studies revealed that S100B does not correlate with the estrogen-negative group of cancer." (PMID 39335163, 2024). "Also, many cancer-related genes such as IL7, S100B and IER3 showed an altered expression pattern." (PMID 28325946, 2017).